ENSG00000307417 (novel transcript, antisense to EML1)
Gene: Long non-coding RNA gene on chromosome 14 (99,941,862 to 99,949,234, reverse strand). Ensembl gene ENSG00000307417.
Gene Ontology:
Molecular function: pre-mRNA 5'-splice site binding
Biological process: mRNA 5'-splice site recognition
Cellular component: U1 snRNP